BRAF (B-Raf proto-oncogene, serine/threonine kinase)
Diseases named in the same sentence as BRAF in open-access papers (continued):
Sharing a sentence is not in itself a finding about the gene and the disease.
melanoma (continued). "Although immunomodulatory therapy is the only intervention that had ever shown promise in the adjuvant therapy of melanoma, there is now evidence that molecularly-targeted therapies can benefit patients with resected high-risk melanoma whose tumor cells carry an activating BRAF mutation." (PMID 29848375, 2018). "Activating mutations in the BRAF oncogene are found in 40–60% of patients with advanced melanoma." (PMID 29880484, 2018). "Another B-RAF inhibitor, dabrafenib received approval for the treatment of BRAF mutated melanoma while trametinib, a MEK inhibitor has been approved for the same indication, as well as for the treatment of B-Raf mutated NSCLC, both as single agent and in combination with dabrafenib." (PMID 30352565, 2018). "Activating mutations in BRaf have been detected in approximately 60% of melanoma tumors and nevi." (PMID 29464040, 2018). "Indeed, in certain studies, the combination of metformin and a BRAF inhibitor stimulated the proliferation of melanoma cells mutated by NRAS." (PMID 30186236, 2018). "BRAF mutations are actionable in melanomas (OncoKB level 1)." (PMID 30442178, 2018). "More recently, it was reported that patients with BRAF-mutated melanoma were less likely to require combined PD-1 and CTLA4 blockade than others, reinforcing the view that mutation status may predict response to checkpoint blockade." (PMID 29664013, 2018). "This might indicate that the presence of both mutated BRAF and melanoma markers could be used to identify sarcoma patients expected to respond to vemurafenib." (PMID 29570692, 2018). "Most of the melanomas (68.3%) carried a BRAF V600E mutation." (PMID 29266761, 2018). "The use of chemotherapy has been limited by the introduction of targeted therapies, owing to the discovery of a mutation shared by about 50% of melanomas, consisting in the substitution of valine to glutamic acid in codon 600 in the BRAF gene (activating BRAFV600E mutation)." (PMID 29682188, 2018). "The principal aim of the present study was to assess whether MR spectroscopy and diffusion weighted imaging could serve to non-invasively detect response to BRAF/MEK inhibition in BRAF mutated melanoma xenografts." (PMID 29682188, 2018). "Further, BRAF mutations were identified in 6 samples (pediatric n = 2, adult n = 4), including BRAF V600E (n = 2) and other kinase activating mutations, which are commonly seen in melanomas and histiocytic disorders and been highly amenable to BRAF-inhibitor therapy." (PMID 29899868, 2018). "Using thyroid cancer and melanoma cells as cancer cell models that harbored BRAF V600E and TERT promoter mutations, we demonstrated that the BRAF V600E/MAPK pathway promoted the formation and binding of transcriptional GABP complex to the mutated TERT promoter and its activation." (PMID 29422527, 2018). "Other common BRAF mutations were found at the same V600 codon (V600K, about 16% of mutations and V600D/R, 3% of all mutations in melanoma), with slightly higher rates in melanomas arising in older patients." (PMID 29371600, 2018). "Interestingly, our results showed that VB1 also increased the ROS levels in BRAFi (BRAF inhibitor)-resistant melanoma cells, leading to DNA cytotoxicity, which caused G2/M phase arrest and apoptosis." (PMID 30400954, 2018). "One possible explanation for these results could be due to aggressive nature of melanoma with BRAF mutation compared to wild variant." (PMID 30112001, 2018). "This suggests that melanoma cells with high levels of SCD1 may be insensitive to MAPKi treatment and that SCD1 could discriminate BRAF-mutated melanoma into MAPK-sensitive and -resistant subpopulations." (PMID 30558661, 2018). "Here, in advanced melanoma the authors study genomic evolution, highlighting trunk mutations dominated by the ultraviolet damage signature, common late truncal whole-genome duplication events, as well as selective copy number gain of mutant BRAF." (PMID 29991680, 2018).
melanoma (continued). "Also TAMs and TAM-derived TNF-α have been implicated in failure of BRAF inhibitors in mouse melanoma models." (PMID 30233579, 2018). "While therapeutic targeting of RAF and MEK via small molecule inhibitors has been clinically approved for V600E/K-mutated BRAF melanoma, the clinical application of these inhibitors in BRAF mutant NSCLC is at its early stages and requires further preclinical and clinical investigations." (PMID 29662630, 2018). "In addition, the frequency of BRAF or NRAS mutations shows a melanoma subtype and metastatic site dependency." (PMID 30053879, 2018). "This work focuses on the analysis of eNAMPT levels in patients with BRAF-mutated melanoma." (PMID 29721178, 2018). "BRAF mutations seen in melanomas are MAPK pathway activating mutations." (PMID 30360441, 2018). "The aim of this study was to investigate the value of magnetic resonance spectroscopy (MRS) of choline and diffusion-weighted magnetic resonance imaging (DW-MRI) as early markers of response or resistance to targeted therapies for the treatment of BRAF mutated melanoma." (PMID 29682188, 2018). "Indeed, one or several of the signature changes were present in DCCs of 8/9 (89%) patients dying from melanoma (p = 0.048, log-rank test), with BRAF mutation being the most relevant single indicator (p = 0.031)." (PMID 29426936, 2018). "Two of these mutations were ever present on FFPE matched samples (SSM #12 and nodular #9 melanoma), they were detected retrospectively with the Sanger sequencing method, and one BRAF L597S mutation appeared de novo in an acral lentiginous melanoma after stabilization on immunotherapy (#1)." (PMID 30546839, 2018). "We established three BRAF inhibitor-resistant melanoma cell lines with BRAF mutation." (PMID 29929490, 2018). "In addition, reduced levels of DAPK1 were shown to be associated with reduced sensitivity to BRAF inhibitor therapy, suggesting its possible role in targeted melanoma therapy." (PMID 30240750, 2018). "In addition, mutagenome analysis identified a common point mutation within the BRAF (v-Raf murine sarcoma viral oncogene homolog B) protein (BRAFV600E) apparent in >40% of all melanoma cases." (PMID 29983861, 2018). "In advanced malignant melanoma the BRAF V600E mutation can be detected in up to 84% of patients with mutation-positive tumors and the level of mutant DNA (cfBRAFV600E) has been shown to reflect response to targeted treatment including progression and tumor burden." (PMID 30220966, 2018). "Among the most highly significant results, KRAS G12R appeared more strongly selected than other KRAS mutations, including KRAS G12C and G13D, in pancreatic cancer, as did BRAF V600E compared with other BRAF common mutations, including BRAF K601E, in thyroid, melanoma and colorectal cancer." (PMID 29748584, 2018). "This reflects a partially different biological activity of the BRAF mutation depending on the cancer type and suggests that unique mechanisms of resistance may be activated in colorectal cancer compared to melanoma." (PMID 30598662, 2018). "The most frequent mutation is the BRAF mutation which has been found in about 50% of melanomas." (PMID 30693134, 2018). "Although inhibition of BRAF oncoprotein by the small-molecule drug PLX4032 (vemurafenib) is highly effective in the treatment of melanoma, colon cancer patients associated with the same BRAF mutation have poor prognosis showing only a very limited response to this drug." (PMID 29593231, 2018). "However, melanoma cell lines with NRAS mutations appeared to have a greater sensitivity than those with BRAF mutations." (PMID 29435161, 2018).
melanoma (continued). "To evaluate the potential for ctDNA to identify melanoma patients at high risk of relapse following surgery with curative intent, we analyzed ctDNA in the plasma from 161 patients carrying either a BRAF or NRAS mutation in their baseline resected tumor (available at Annals of Oncology online)." (PMID 29112704, 2018). "Of note, this site is more recurrently mutated than the individual TERT C228T/C250T sites and nearly as frequent as chr7:140453136 mutations (hg19) pertaining to BRAF V600E, thus representing the second most common mutation in melanoma and likely other skin cancers." (PMID 30586386, 2018). "Melanoma patients with BRAF mutations are usually treated with BRAF inhibitors such as vemurafenib, but responses are short-lived as drug resistant tumors metabolically switch to mitochondrial oxidative phosphorylation (OXPHOS) to escape metabolic stress-induced BRAF inhibition." (PMID 30651927, 2018). "However, a 61kDa BRAF (V600E) isoform, encoded by a splice variant with an exon 4–8 skipping event, is expressed in melanoma patients exhibiting resistance to vemurafinib." (PMID 30463359, 2018). "In melanoma, the most common driver mutation occurring in over 50% of patients affects the serine/threonine protein kinase BRAF (BRAFV600E), a downstream effector of growth factor receptor signaling, that can be therapeutically targeted by specific BRAFV600mut inhibitors (BRAFi)." (PMID 29794999, 2018). "Seventy-four patients were included: 33 wild-type and 41 BRAF-mutated melanoma." (PMID 29970025, 2018). "Furthermore, MAPK-activated RSK, which directly phosphorylates PFKFB2, is required to maintain glycolytic metabolism in BRAF-mutated melanoma cells." (PMID 30234009, 2018). "Dramatic responses to the BRAF inhibitor, vemurafenib, and preclinical as well as early clinical reports of enhanced antigen expression and a favorable tumor microenvironment in patients treated with such targeted agents led to our attempt to combine this agent in BRAF-mutated melanoma." (PMID 30053905, 2018). "Whereas a select few assays, for example, APC or KRAS mutations in colorectal cancer, BRAF in melanoma encompass a significant proportion of patients, and are thus reliable aberrations to use a surrogate for tumour fraction, the equivalent targets have yet to be demonstrated in MIBC." (PMID 30158468, 2018). "In 2011, Long and colleagues found that BRAF mutations were related to a high incidence of melanoma, including earlier age of onset, shortened survival, and lack of chronic skin damage, suggesting the importance of inhibiting mutated BRAF in a population of 197 patients." (PMID 30544544, 2018). "Eligible patients were HD IL-2 eligible with metastatic BRAF V600 mutated melanoma." (PMID 30053905, 2018). "Approximately 60% of melanomas contain a V600E mutation in the BRAF gene." (PMID 30100999, 2018). "Sustained responses were observed mostly in BRAF or NRAS-mutated melanoma." (PMID 28954413, 2017). "Differences in RCM parameters between BRAF mutated and wild type melanoma was observed." (PMID 28662062, 2017). "One of the BRAF mutated melanomas evolved from a background of PAM." (PMID 28938534, 2017). "In BRAF-mutated melanoma, CRAF and RAS activities are diminished by activated BRAF." (PMID 28474232, 2017). "Furthermore, approximately 8 % of human tumors have mutations in BRAF (a member of the RAF family) — melanoma, thyroid cancer, and CRC have been associated with a high frequency of BRAF mutations." (PMID 27650277, 2017). "Interestingly, in case 4 we observed a BRAF V600E mutation in the primary melanoma, undetectable in the paired metastasis, which instead revealed a NRAS Q61R mutation." (PMID 28039443, 2017). "As the studies of the major genomic aberrations in melanoma have been extensively reviewed elsewhere, this section will describe a number of the most common driver mutations seen in cutaneous melanoma [BRAF, NRAS, NF1, microphthalmia-associated transcription factor (MITF), and PTEN]." (PMID 29276510, 2017).
melanoma (continued). "From a clinical perspective of the treatment of BRAF‐mutated melanomas, this synergism could be exploited with either immune‐checkpoint modulators (Anti‐PD1 Ab or Anti CTLA‐4) or with approaches based on adoptively transferred antitumor lymphocytes." (PMID 27974353, 2017). "Based on the finding that cell survival in these tumours actually depends on this pathway, ground-breaking progress has been made in the treatment of BRAF-mutated advanced melanoma over the last years owing to the development of specific inhibitors targeting BRAFV600E/K or MEK." (PMID 28415756, 2017). "Resistance mechanisms have been studied extensively in BRAF-mutated melanomas and it could be demonstrated that various genetic mechanisms ranging from BRAF gene amplification to alternative driver gene mutations may mediate BRAF inhibitor resistance." (PMID 28886708, 2017). "This latter type melanoma was found to be associated with BRAF V600E mutations." (PMID 28662062, 2017). "According to the result of two parts, we suggested that LKB1 silencing cooperating with BRAF V600E mutation could effectively enhance the invasion and migration potentials of the melanoma cells." (PMID 29371951, 2017). "Up to 70% of patients diagnosed with melanoma and approximately 50% of patients with the advanced form of melanoma possess a mutation in the BRAF gene, leading to aberrant activation of the mitogen-activated protein kinase (MAPK) pathway, a well-documented cancer pathway." (PMID 28052762, 2017). "We have repeatedly observed that some BRAF‐mutated sensitive melanoma cell lines treated with low‐dose suboptimal vemurafenib (i.e., 20 nmol/L and up to 100 nmol/L depending on the cell lines) may paradoxically proliferate." (PMID 28573821, 2017). "In addition, all 26 NF1 mutant BRAF-RAS wild-type melanomas carried mutations in other known RASopathy genes, including RASA2, PTPN11, SOS1, RAF1 and SPRED1." (PMID 28637487, 2017). "However, paradoxical activation of the MAPK/ERK pathway by BRAF inhibitors is observed in NRAS-mutated melanoma and results from the recruitment of inhibited BRAF at the membrane where it acts as a scaffold to enhance CRAF activity." (PMID 28497782, 2017). "Indeed, lapatinib, a clinical ERBB2 and EGFR inhibitor, effectively inhibited the ERBB3/ERBB2 pathway and importantly, delayed melanoma tumor growth in both mutated and wild type BRAF cells." (PMID 28060735, 2017). "Furthermore even when an effective target is identified, clinical responses are often followed by progression due to the development of resistance as seen in patients with BRAF mutated melanoma treated with BRAF mutant inhibitors." (PMID 27845911, 2017). "We tested the hypothesis that a 4-month course of adjuvant dabrafenib in stage IIIC BRAF-mutated melanoma would improve 2 year RFS from 24% to 51%, and that tumor-derived cell free DNA (cfDNA) in plasma would correlate with and predict recurrence." (PMID 29285228, 2017). "Also, it should be noted that only ∼50% of melanomas carry the BRAF mutation, and that BRAF mutations are very rare in uveal melanoma." (PMID 28103611, 2017). "Consistently, we could also observe a detrimental effect of RSK inhibition on BRAF-mutated melanoma cells which are still sensitive to vemurafenib treatment." (PMID 28415756, 2017). "The recent introduction of routine genotyping for germline MC1R variants and somatic NRAS and BRAF mutations may also help to identify individuals at highest risk of melanoma development in the future." (PMID 28078671, 2017). "A major breakthrough was achieved in 2002 with the discovery of activating mutations in the serine/threonine kinase BRAF in nearly every second malignant melanoma leading to a constitutive activation of the mitogen-activated protein kinase (MAPK) signalling pathway." (PMID 28415756, 2017).
melanoma (continued). "Our hypothesis led to the identification of DUSP6 as a potential synthetic lethal target in melanoma with BRAF V600E mutation and high expression of DUSP6, suggesting that, in certain scenarios, this tumor suppressor may serve as drug target." (PMID 28423600, 2017). "In total, 134/253 (53.0%) melanoma patients carried BRAF mutations." (PMID 28881731, 2017). "Among the 138 patients with BRAF V600E-mutated melanoma, 40 cases (29.0%) showed EZH2 gain." (PMID 29202777, 2017). "Although there is evidence that mutant BRAF could trigger immune responses in melanoma cells under certain contexts, our data are more consistent with a diminished chance of clinical benefit to ipilimumab in patients with BRAF mutations." (PMID 29157311, 2017). "BRAF inhibitors are effective anticancer agents in BRAF-mutated melanomas." (PMID 29033690, 2017). "Moreover, oncogenic BRAF mutations are thought to be even more important than mutations in RAS genes for activating the MAP kinase pathways in certain cancers particularly melanoma and thyroid cancer." (PMID 28422736, 2017). "Also, the combination effect appeared as representative for melanoma cells as seen in 3/3 BRAF-mutated melanoma cell lines." (PMID 28151482, 2017). "Although melanoma patients with oncogenic BRAF V600E mutation have poor prognosis, yet its involvement in invasion that is clinically observed in melanoma patients remains unclear." (PMID 29371951, 2017). "We have demonstrated that presence of immune cells in association with tumor proliferation and BRAF mutation status may further contribute to identify stage III melanoma patients with high risk of relapse." (PMID 28851300, 2017). "Both melanoma cell lines used in the current study have BRAF mutations, hence these cell lines could possibly be targeted using a number of drugs such as vemurafnib, dabrafenib, trametinib, or a combination of either these drugs." (PMID 28890854, 2017). "NRAS and BRAF activations rarely occur in the same melanoma, albeit NRAS mutations being observed in patients with advanced BRAF tumors who had failed BRAFi therapy and which therefore may mechanistically contribute to resistance to BRAFi treatment." (PMID 29276510, 2017). "EZH2 gain-of-function mutations often occur concurrently with the BRAF V600E mutation in melanoma." (PMID 29202777, 2017). "Furthermore, the median allele frequency of PMS2 promoter mutations in melanoma is 0.26 (range 0.05–0.85), which is lower than that for BRAF V600 mutations occurring in the same tumor type (median 0.37, max 0.97)." (PMID 28420421, 2017). "This study aimed to define the probability and distribution of BRAFV600 mutations, and the clinico-pathological factors that may affect BRAF mutation status, in patients with advanced melanoma using next-generation sequencing." (PMID 29176861, 2017). "BRAF mutations are commonly identified in melanoma, in which the BRAF mutation rate is more than 60%, offering hope that inhibition of BRAF kinase activity could benefit melanoma patients." (PMID 28368335, 2017). "Thus, in melanoma, one sample (6.2%) had an uncommon BRAF (c.1400C>T; p.Ser467Leu) mutation, one (6.2%) had an NRAS (c.385C>T; p.Gln129*) mutation, and rare EGFR, ERBB2, KRAS, and MET mutations were also exhibited in one sample (6.2%)." (PMID 28404952, 2017). "Finally, treatment with benzbromarone, a specific inhibitor of EYA1, caused significant inhibition of melanoma cell proliferation, and increased sensitivity to the BRAF inhibitor vemurafenib." (PMID 29285235, 2017). "We did note that the BRAF V600E mutation is distinctly associated with higher T cell estimates, but this is only observed in thyroid cancer, despite the prevalence of this mutation in melanoma and occurrence in other tumor types." (PMID 28749946, 2017).